ATF4 (activating transcription factor 4)
Diseases named in the same sentence as ATF4 in open-access papers (continued):
Sharing a sentence is not in itself a finding about the gene and the disease.
Hepatic steatosis (continued). "Among the three essential pathways for unfolded protein response induced by ER stress, PERK-eIF2α-activating transcription factor 4 (ATF4) signaling regulates lipogenesis and hepatic steatosis by activating lipogenic genes, such as SREBP-1c27." (PMID 27045862, 2016). "Similarly, phosphorylated PERK induces the phosphorylation of eIF2α and the expression of ATF4, further promoting the pathological process of liver steatosis." (PMID 38638434, 2024). "Similarly, phosphorylated PERK induces the phosphorylation of Eukaryotic Translation Initiation Factor 2 Subunit Alpha (eIF2α) and the expression of Activating Transcription Factor 4 (ATF4), which promotes liver steatosis, IR and hepatocyte damage." (PMID 37660122, 2023). "The previously published studies showing that Atf4 deletion protected mice from liver steatosis supports that the activation of the mitochondrial ISR might exacerbate NASH." (PMID 35940556, 2022). "Furthermore, various components of ER stress play roles in regulation of lipid metabolism, and the PERK-eIF2α-ATF4 pathway has been identified as a critical component required for regulating lipogenesis and hepatic steatosis." (PMID 35315506, 2022). "ATF4 liver-specific knockout mice are protected from HFD or HCD-induced liver steatosis." (PMID 33670323, 2021). "However, ATF4 overexpression induces early onset of hyperlipidemia and hepatic steatosis in zebrafish." (PMID 33670323, 2021). "Thus, the potential mechanism of MSC administration ameliorated hepatic steatosis was possibly through down‐regulation of the SREBP1 expression by the decreased ATF4 expression, resulting in a reduced lipogenesis." (PMID 33591626, 2021). "Interestingly however, exercise-trained GCN2KO mice were better protected against hepatic steatosis with downregulated expressions of p-eIF2α and ATF4, upregulated expressions of p-AMPK and SIRT1, and the presence of PPARα in the liver, compared to the exercised WT mice." (PMID 33299856, 2020). "Similarly, in a methionine/choline-deficient diet-induced hepatic steatosis model, SESN2 expression could be enhanced in a manner that was dependent on the PERK/eIF2α/ATF4 pathway, and it ameliorated hepatic steatosis progression through autophagy activation." (PMID 31867002, 2019). "Data from an animal study showed that knee loading significantly decreased the histological severity of hepatic steatosis and downregulated biomarkers related to ER stress (e.g., GRP78, p-eIF2α, and ATF4) compared to those of obese mice." (PMID 35315506, 2022). "Consistent with previous publications, hepatocyte ATF4 ablation inhibited hepatic steatosis, reinforcing the notion that hepatic steatosis per se is not damaging and does not increase cancer risk unless it is accompanied by liver damage." (PMID 36996941, 2023). "The PERK-eIF2α-ATF4 pathway leads to the up- regulation of UPR target genes and induces the proapoptotic protein C/EBP homologous protein (CHOP), regulating both lipogenesis and hepatic steatosis." (PMID 35958574, 2022). "We observed early-onset hyperlipidaemia and liver steatosis in ATF4 transgenic zebrafish (ATs) without doxycycline treatment (ATs − Dox)." (PMID 29180630, 2017). "Hepatic steatosis and lipogenesis are regulated by the PERK-eIF2α-ATF4 pathway." (PMID 26840310, 2016). "Consistent with a previous study 6, HFD induced hepatic steatosis in Atf4+/+ mice, but not in Atf4−/− mice, as demonstrated by oil red O and haematoxylin and eosin staining and significant hepatic and serum TG accumulation in Atf4+/+ mice." (PMID 24373582, 2014). "The protection against diet-induced hepatic steatosis present in OPA1 BAT KO and OPA1/FGF21 BAT DKO mice was no longer observable in the absence of ATF4 induction in OPA1 BAT KO mice." (PMID 33944779, 2021).
colorectal cancer (34 papers, 2010 to 2025). A primary or metastatic malignant neoplasm that affects the colon or rectum. "The involvement of ATF4 in glutamine starvation-induced IL-8 expression was further confirmed in the glutamine-addicted RKO colorectal cancer cell line under conditions of apoptosis inhibition." (PMID 40683891, 2025). "In summary, the ATF4/SLC1A5 axis plays a significant role in the progression of colorectal cancer by regulating glutamine metabolism and glycolysis." (PMID 39696988, 2024). "Our observation revealed that the expression levels of p‐eIF2α and ATF4 were consistently elevated and positively correlated in colorectal cancer samples after radiotherapy." (PMID 38520732, 2024). "For example, the glutaminolysis inhibitor was found to induce pro-survival autophagy via activating ATF4, which compromised its efficacy against colorectal cancer." (PMID 36778128, 2023). "Studies have reported that the transcriptional activation of ATF4 promotes colorectal cancer proliferation." (PMID 36900220, 2023). "During glutaminolysis inhibition in colorectal cancer, activating transcription factor 4 (ATF4) is increased to reduce mTOR signaling by transcriptionally activating the mTOR suppressor DNA damage-inducible transcript 4 (DDIT4)." (PMID 36900220, 2023). "Serine starvation leads to the activation of ATF4 as a protective stress response to cellular amino acid starvation in a series of colorectal cancer cell lines." (PMID 35743178, 2022). "From this study, the mechanism of actions of green tea EGCG in colorectal cancer was elucidated via the induction of the ER stress particularly through PERK/p-eIF2α/ATF4 and IRE1α pathways, which eventually lead to apoptosis." (PMID 31930117, 2019). "In colorectal cancer, overexpression of ATF4 has been related to oxaliplatin and 5-fluorouracil resistance, while ATF4 downregulation delayed tumour growth of endometrial cancer xenografts." (PMID 30134550, 2018). "Recent studies found that ONC201 can induce the ATF4-mediated integrated stress response to inhibit the growth of colorectal cancer cells and leukemia/lymphoma cells." (PMID 28423492, 2017). "An increase in ATF4 is consistent with recent studies in other cancer cell types including leukemia, lymphoma and colorectal cancer cells." (PMID 28423492, 2017). "recently reported that ATF4 promotes glycolysis under the condition of colorectal cancer." (PMID 41479926, 2025). "SLC1A5 and ATF4 expression levels are detected in colorectal cancer tissues." (PMID 39696988, 2024). "In the present study, we found that shikonin induced the cell apoptosis of colorectal cancer cells by activating the ER stress through the PERK/elF2α/ATF4/CHOP and IRE1α/JNK signaling pathways, up-regulating the anti-apoptotic protein Bcl-2 and increasing the expression of caspase-3/9." (PMID 34976186, 2022). "And depletion of ATF4 significantly inhibits colorectal cancer cell growth in vitro and in vivo." (PMID 34709767, 2021). "Moreover, the PERK-eIF2a-ATF4 branch of the UPR pathway plays a role in tolfenamic acid-induced apoptosis in colorectal cancer cells, as silencing ATF4 attenuates tolfenamic acid-induced apoptosis." (PMID 33050301, 2020). "Significantly elevated levels of ER stress markers such as GRP78 (78 kDa glucose-regulated protein), ATF4 (activating transcription factor 4), and CHOP (homologous protein C/EBP) were observed in colorectal cancer cells treated with ACAT inhibitor." (PMID 39940954, 2025). "Through autophagy activation and PERK/ATF4/CHOP signaling pathway stimulation, it triggers colorectal cancer cell apoptosis while synergistically enhancing 5-FU-mediated cytotoxic effects." (PMID 40136455, 2025). "ATF4 is a downstream target of URB1 and is involved in the oncogenic role of URB1 in colorectal cancer.Our study demonstrated, for the first time, how transcriptional control of the SHH protein by ATF4 affects the development of gastric cancer." (PMID 36900220, 2023).
colorectal cancer (continued). "Then, Bax, PERK/eIF2α/ATF4/CHOP and other ER stress apoptotic pathway proteins be further activated, resulting in the apoptosis of colorectal cancer cells." (PMID 34659567, 2021). "From this study, it was revealed that the treatment of EGCG on colorectal cancer cell lines, HT-29, had induced the expressions of UPR-related proteins which are BiP, PERK and its downstream targets (p-eIF2α and ATF4), and IRE1α." (PMID 31930117, 2019). "The treatment with CBD led to an increase in ATF4 levels followed by apoptosis in HCT116 and DLD-1 colorectal cancer cells; the upregulation of ER stress biomarkers, such as ATF4 and GRP78, was also reported in pancreatic cancer cell models after treatment with the phytocannabinoid." (PMID 39594426, 2024). "Taken together, our results demonstrate that GREM1 is an invasion-promoting factor via regulation of ATF6 and ATF4 expression in CRC cells, suggesting GREM1 may be a potential pharmacological target for colorectal cancer treatment." (PMID 35883579, 2022). "Similar, rapid phosphorylation of GCN2 and expression of ATF4 was observed in Dabrafenib-stimulated colorectal cancer cells, regardless of whether they exhibited paradoxical activation of ERK1/2 (HCT116 cells, KRASG13D) or inhibition of ERK1/2 (HT29 cells, BRAFV600E)." (PMID 41249187, 2025). "ICG-001 activates an early ER stress pathway including activating transcription factor 4 (ATF4), DNA damage inducible transcript 3 (DDIT3), and tribbles pseudokinase 3 (TRIB3) in sensitive as opposed to resistant colorectal cancer cell lines." (PMID 29290987, 2017).
pancreatic cancer (33 papers, 2014 to 2025). "In the context of melanoma and pancreatic tumors, a conditional knockout of ATF4 results in delayed tumor growth due to deficient vascularization." (PMID 37601686, 2023). "The significance of the ATF4/TXNIP/REDD1/mTOR pathway was further supported by associated expressions in xenograft tumors as well as human pancreatic cancer samples." (PMID 38089448, 2022). "In this study, we assessed the potential role of ATF4 in CB-839-induced pancreatic cancer cell resistance and explored strategies to enhance CB-839 efficacy in pancreatic cancer cells." (PMID 40223274, 2025). "Our experiments confirmed that CB-839 treatment induces ATF4 expression in pancreatic cancer cells through the GCN2-ATF4 signaling pathway." (PMID 40223274, 2025). "In summary, our findings demonstrate that ATF4-mediated upregulation of ASCT2 contributes to resistance against CB-839 in pancreatic cancer cells." (PMID 40223274, 2025). "Researchers found that ceramide has a function in the apoptosis of pancreatic cancer cells caused by THC, namely, in the increased expression of ATF‐4, p8, and TRB3 in pancreatic cancer cells." (PMID 38690008, 2024). "On the other hand, ATF4 has recently been shown to enhance transcription of HIF1α in long-term hypoxia in pancreatic cancer, what would explain detection of HIF1α protein in our hypoxia adapted cells." (PMID 37123244, 2023). "More importantly, analysis of human pancreatic cancer samples revealed significant downregulation of ATF4, TXNIP, and REDD1 in the tumor tissues compared to matching normal tissues." (PMID 38089448, 2022). "To investigate the role of ATF4 in pancreatic cancer progression, we first analyzed ATF4 expression in pancreatic cancer tissues and cancer cell lines and analyzed its correlation with pancreatic cancer patient prognosis." (PMID 33782384, 2021). "These experiments indicated that ATF4 participated in regulating the cellular proliferation and migration capability of pancreatic cancer." (PMID 33782384, 2021). "The results of the IHC assay also showed that ATF4 staining was positive in pancreatic cancer tissue samples." (PMID 33782384, 2021). "We demonstrated that TGF-β1 derived from CAFs upregulates the expression level of ATF4 in pancreatic cancer cells via the SMAD2/3 pathway." (PMID 33782384, 2021). "CCK8 analysis showed that CAFs promoted the growth of pancreatic cancer cells, but silencing ATF4 partially inhibited the growth-promoting effect of CAFs." (PMID 33782384, 2021). "In the present work, we demonstrated that CAFs secrete TGF-β1 to upregulate the expression of ATF4 in pancreatic cancer cells via the SMAD2/3 pathway." (PMID 33782384, 2021). "Taken together, these analyses suggested that CAFs accelerate the malignant progression of pancreatic cancer via the upregulation of ATF4." (PMID 33782384, 2021). "Then, Transwell assays were performed to detect the role of ATF4 expression in regulating the migration and invasion of pancreatic cancer cells." (PMID 33782384, 2021). "Combined analysis of data from TCGA and the genotype-tissue expression (GTEx) database showed that the expression of ATF4 was significantly upregulated in pancreatic cancer tissues." (PMID 33782384, 2021). "The CCK8 assay showed that silencing ATF4 suppressed pancreatic cancer PANC-1 and BxPC-3 cell growth." (PMID 33782384, 2021). "Compared with the normal pancreatic ductal epithelial cell line HPDE6-C7, ATF4 was significantly upregulated in pancreatic cancer cell lines such as PANC-1, BxPC-3, CFPAC-1, MIA PaCa-2, and SW1990." (PMID 33782384, 2021). "Importantly, the ATF4-glutamine metabolic axis acts as a critical node integrating metabolic and stress signaling, playing an essential role in cancer biology (Novel functions of ATF4 in early stages of pancreatic cancer tumorigenesis)." (PMID 40830338, 2025).
pancreatic cancer (continued). "However, in pancreatic cancer cells, our findings indicate the presence of metabolic adaptive mechanisms, such as ATF4-mediated upregulation of ASCT2 expression." (PMID 40223274, 2025). "Therefore, targeting the PERK/eIF2a/ATF4 pathway can be used to inhibit EMT in pancreatic cancer cells." (PMID 37790807, 2023). "ATF4 promotes pancreatic cancer progression and the mechanism of gemcitabine resistance." (PMID 36209075, 2022). "We also noted that this correlation was stronger in patients with grade 2 compared with grade 3 pancreatic cancer, which suggests that ATF4 may exert a stronger regulatory role on collagen deposition at earlier disease stages." (PMID 35654839, 2022). "Although their downregulation could be simply a bystander event during pancreatic cancer development, our findings revealed that the upregulations of ATF4, TXNIP, and REDD1 were concomitant with the therapeutic benefits of GW3965." (PMID 38089448, 2022). "In addition, we performed qRT-PCR assays on 60 PDAC tissue samples and matched normal adjacent tissue samples, and the results showed that ATF4 was significantly overexpressed in pancreatic cancer tissues." (PMID 33782384, 2021). "However, the specific roles of ATF4 in CAFs promoting pancreatic cancer progression and the mechanism of gemcitabine resistance are still poorly elucidated." (PMID 33782384, 2021). "Moreover, PERK-mediated ATF4 activation has exhibited protective roles against erastin-induced ferroptosis in pancreatic cancer cells." (PMID 31519193, 2019). "Indeed, BxPC-3 pancreatic cancer cell line exhibited both the capacity to grow in amino acid-deprived medium and a low level of ATF4 expression." (PMID 28460466, 2017). "p-ERK-mediated ATF4 activation can also protect pancreatic cancer cells from ferroptosis, and evidence shows that cystine starvation can increase the phosphorylation of eIF2α, as well as the expression of ATF4, in human triple negative breast cancer (TNBC) cells, resulting in ferroptosis." (PMID 35784729, 2022). "Therefore, our results suggest that the expression levels of ATF4 may affect the efficacy of drugs that target ER stress signaling in the treatment of pancreatic cancer." (PMID 35283426, 2022). "Interestingly, the ATF4 levels were upregulated after treatment with gemcitabine in pancreatic cancer cells and could be regarded as a mechanism for induction of apoptosis." (PMID 31582720, 2019). "PA promoted the expression of XBP-1s, ATF4, CHOP, and p-eIF2α in pancreatic cancer cells through ER stress, which promoted ER stress and led to apoptosis." (PMID 39312302, 2024). "In the case of pancreatic cancer, cells relying on glycolytic pathways for energy have perpetually active ISR through GCN2-mediated ATF4 expression." (PMID 37601686, 2023). "Downregulation of ATF4 levels decreased the IC50 value of gemcitabine, suggesting that silencing ATF4 expression can enhance sensitivity to gemcitabine in pancreatic cancer cells." (PMID 33782384, 2021). "The results showed that silencing ATF4 expression downregulated the migration ability of PANC-1 and BxPC-3 pancreatic cancer cells." (PMID 33782384, 2021). "Translation factors, such as the PERK/eIF2/ATF4 signaling pathway, have been involved in EMT in pancreatic cancer cells." (PMID 34922580, 2021). "A rapid increase in the phosphorylation of PERK and eIF2α, as well as a remarkable upregulation of ATF4 and CHOP, suggested that PMN-Spt incubation led to a potent ER stress response in these pancreatic cancer cells." (PMID 34131176, 2021). "MAPK inhibition attenuates translational induction of ATF4 and the expression of its target ASNS, as well as sensitizes the pancreatic tumor to asparagine restriction; this is reflected by tumor growth inhibition." (PMID 33198082, 2020). "Asparagine restriction in pancreatic cancer cells activates receptor tyrosine kinase-MAPK signaling and enhances translation of activating transcription factor 4 (ATF4) mRNA." (PMID 33198082, 2020).